TNF (tumor necrosis factor)
Diseases named in the same sentence as TNF in open-access papers (continued):
Sharing a sentence is not in itself a finding about the gene and the disease.
cardiovascular disease (continued). "miR-34a influences lipid metabolism by inhibiting the Sirtuin 1 (SIRT1) pathway as well as stimulating pro-inflammatory cytokines such as IL-1b, IL-7A CRP and TNF-α which are strongly associated with cardiovascular diseases." (PMID 36071532, 2022). "Some authors reported that increasing in serum levels of some pro-inflammatory cytokines (IL-1b, IL-8, and TNF-α) goes along with the increment of cardiovascular diseases risk." (PMID 36096730, 2022). "It seems that evaluation of cardiovascular disease risk in OSAS patients based on TNF-α blood levels in OSAS patients would be a valuable complement to the previous studies." (PMID 36430593, 2022). "Numerous clinical and animal studies also suggested the opportunity to prevent cardiovascular diseases or their underlying risk factors with anti-tumor necrosis factor strategies." (PMID 35074627, 2022). "CR decreases intramyocellular lipid content, blood pressure, total cholesterol, LDL cholesterol, C-reactive protein, TNFα, and 10-year risk of cardiovascular disease." (PMID 36589143, 2022). "We observed results indicating potentially lower risk of ADRD with TNF inhibitors in patients with a history of cardiovascular disease in a subgroup analysis." (PMID 35394510, 2022). "Inflammatory mediators such as TNF-α and IL-6 released during these conditions are tightly linked to pathological cardiovascular diseases, including drug intoxication." (PMID 34548593, 2021). "For example, ginger has a significant effect on reducing circulating C-reactive protein (CRP) and tumor necrosis factor-alpha (TNF-α) levels, which are systemic inflammatory markers associated with an increased risk of cardiovascular disease." (PMID 34055012, 2021). "Elevated plasma levels of TNF-α are associated with inflammation and are a risk factor for cardiovascular disease." (PMID 32793203, 2020). "Using two large United States insurance claims databases, it was recently shown that abatacept is associated with a 20% reduced risk of cardiovascular diseases when compared to TNF inhibitor." (PMID 32556473, 2020). "Interleukin (IL)-8 and TNF-α are critical molecules that arre associated with cardiovascular diseases, and we showed that DOX increased the expression of IL-8 and TNF-α." (PMID 32354131, 2020). "TNFα is a pro-inflammatory cytokine with a wide range of biological effects that has been implicated in the pathophysiology of many cardiovascular diseases." (PMID 32722688, 2020). "It should be noted that as in other cardiovascular diseases, pathogenic TNF-α signaling is mainly mediated by TNFR1." (PMID 33053859, 2020). "For example, arterial stiffening in cardiovascular diseases is associated with an increase in IL-1β, IL-12, TNFα, and MCP-1 as measured from blood plasma." (PMID 32244521, 2020). "The risk of cardiovascular disease was shown to increase when the blood TNF-α concentration was >6 pg/mL." (PMID 31137855, 2019). "A total of 17 vedolizumab and 1074 anti-TNF-associated reports detailed an AE related to cardiovascular disease; most of these reports were associated with serious outcomes (88.2% and 85.7%, respectively)." (PMID 31800627, 2019). "In contrast, in individuals at high risk of cardiovascular disease, flavonoids were found to decrease TNF-α levels in at least 30% of interventions (5/17)." (PMID 30234017, 2018). "Clinically, increases in plasma IL-6 and TNF-α have been associated with cardiovascular disease and disease outcomes." (PMID 29157250, 2017). "Sphingomyelin lipids also correlate positively with plasma IL-8 and TNFα in obese subjects and are implicated in the development of cardiovascular disease due to their promotion of pro-inflammatory signalling pathways." (PMID 28798136, 2017). "IH causes a transition to increased circulating TNF-α and IL-6 levels that is a factor in the development of cardiovascular diseases in OSA patients." (PMID 27977796, 2016).
cardiovascular disease (continued). "TNFα, sICAM-1, and sVCAM-1 were either a determinant of or associated with cardiovascular disease all-cause mortality." (PMID 27459718, 2016). "These include interleukin‐2, interleukin‐6, and TNF‐α, each of which has been linked to both aging and cardiovascular disease." (PMID 27071935, 2016). "Symbiotic supplementation can reduce serum hs-CRP, IL-6 and TNF-α concentrations, a risk factor for cardiovascular diseases." (PMID 26153197, 2015). "It has long been established that the development of chronic auto-inflammatory conditions, including RA and several cardiovascular diseases, is associated with elevated levels of pro-inflammatory cytokines such as IL-1β, IL-6 and TNF." (PMID 26474486, 2015). "Elevated levels of interleukin 6 (IL-6) and tumor necrosis factor alpha (TNFα), produced by the immune system play an important role in increasing the risk of cardiovascular disease." (PMID 26312203, 2015). "In conclusion, symbiotic supplementation can reduce serum hs-CRP, IL-6 and TNF-α concentrations, a risk factor for cardiovascular diseases." (PMID 26153197, 2015). "Multiple cardiovascular disorders are associated with increased levels of circulating pro-inflammatory cytokines, especially TNF-α and IL-6, which are related to a common cytokine profile found in acute and chronic HF patients independently of etiology." (PMID 25303100, 2014). "The effect on TNF-α in subjects with a presence or high risk of cardiovascular disease was significant in only a few studies." (PMID 24505395, 2014). "Patients with high levels of circulating TNFα have a greater risk of developing cardiovascular disease." (PMID 24804145, 2014). "TNF-α plays a pleiotropic effect in the pathogenesis of several metabolic and inflammatory disorders, which are also risk factors for cardiovascular diseases." (PMID 23437105, 2013). "Elevated levels of monocyte chemoattractant protein (MCP-1), interleukin 6 (IL6), and tumor necrosis factor alpha (TNFα), produced by the immune system play important roles in increasing the risk of cardiovascular disease." (PMID 22883023, 2012). "Parameters of chronic inflammation such as plasma hs-CRP, TNFα and IL-6, which are risk factors for cardiovascular disease, remained unchanged, as did plasma adiponectin, which is thought to reduce the risk for cardiovascular diseases." (PMID 22188761, 2011). "Increased tumor necrosis factor (TNF)-α expression has been reported in response to estrogen deficiency which coincides with increased bone loss and cardiovascular disease risk associated with menopause." (PMID 17825101, 2007). "Furthermore, oral glucocorticoids or tumor necrosis factor-alpha (TNF-alpha) inhibitors also increase the risk of cardiovascular disease, and thus, patients with RA are more likely to be on these agents than the general population." (PMID 40225516, 2025). "In addition, interleukin (IL) 1β, IL-6, or tumor necrosis factor (TNF) are reported to affect cardiovascular disease by circulating throughout the body and causing responses in other tissues." (PMID 39093905, 2024). "Pro-inflammatory cytokines such as TNF, IL-1β, and IL-6, secreted by monocytes, enhance their migratory potential towards tissue sites of inflammation and are associated with an increased risk of cardiovascular disease in patients with CKD." (PMID 38558798, 2024). "Similarly, the pathogenesis of metabolic and cardiovascular diseases is intimately linked with the activity of proinflammatory cytokines such as tumor necrosis factor-alpha (TNF-α) and interleukin-6 (IL-6)." (PMID 38398830, 2024). "Moreover, a meta-analysis about the effects of PTX on inflammatory markers in cardiovascular diseases showed that the anti-inflammatory effect of PTX was associated with a statistically significant reduction in the concentrations of TNF-α and CRP in plasma." (PMID 37107001, 2023). "High TNF-α levels have also been linked to the development of cardiovascular disease." (PMID 37887854, 2023).
cardiovascular disease (continued). "As both a cause and a result of cardiovascular diseases, inflammatory cytokines, such as interleukin-1 (IL-1), interleukin-6 (IL-6), tumor necrosis factor (TNF), galectin-3, and others, have a very significant positive link with the pathophysiology and development of these conditions." (PMID 36186974, 2022). "Elevated TNF-α levels are associated with a higher risk of metabolic and cardiovascular disease." (PMID 36430593, 2022). "Surgical treatment for OSA could reduce plasma TNF-alpha levels and decrease the risk of cardiovascular disease." (PMID 35956028, 2022). "Shortening telomerase is associated with disturbances in the immune system and inflammation, increased pro-inflammatory cytokine tumor necrosis factor α that characterizes older adults, and increased risk for Alzheimer’s disease, diabetes, and cardiovascular diseases." (PMID 36589143, 2022). "However, reducing body weight and body fat through regular exercise decreases TNF-α concentration and enhances inflammation and insulin sensitivity, thereby lowering the risk of cardiovascular disease and metabolic disorders." (PMID 34200794, 2021). "In another clinical trial that examined the 5-year cardiovascular events in patients with psoriasis, which was associated with cardiovascular disease, anti-TNF-α antibody therapy was shown to significantly reduce the cardiovascular risk compared with other treatments." (PMID 34071276, 2021). "In anti-TNF-exposed patients, cardiovascular disease associated with serious infections (aHR 3.279, 95% CI 1.098–9.790, p = .033) and the presence of multiple comorbidities (aHR 9.138 (1.248–66.935), p = .029) with malignancies, while patient age did not associate with safety outcomes." (PMID 32860081, 2020). "Therefore, SDG reduces IL-1β, TNF-α, and IL-6 expression, which indirectly reduce the damage of endothelial cells and the risk of cardiovascular disease." (PMID 32684834, 2020). "Increased risk of cardiovascular disease with genetically predicted high TNF level sheds light on the usage of anti-TNF medicine as a potential prevention approach for people with excessive risk of CVD and a potential treatment strategy for patients with impaired cardiovascular condition." (PMID 32805626, 2020). "Hypertrophic adipocytes increase the generation of inflammatory cytokines such as tumor necrosis factor-α (TNFα) and interleukin-6 (IL-6), which may cause chronic inflammation and increase the risk of developing cardiovascular disease." (PMID 31540318, 2019). "As IL-18 induces the production of TNFα which, in turn, supports the synthesis of IL-6, IL-18 might well be responsible for a high risk of cardiovascular disease in obese patients." (PMID 27747236, 2016). "Increased secretion of inflammatory cytokines is thought to be involved in pathogenesis of numerous aging diseases, and clinical trials strongly support a link between increased levels of TNF-α and IL-6 with menopause-related bone loss and cardiovascular diseases." (PMID 26640615, 2016). "The mechanism by which OSAS is associated with cardiovascular disease is not fully understood, but activation of the inflammatory cascade, potentially involving TNF-α, IL-6, or C-reactive protein (CRP), may be an underlying cause of these disease states." (PMID 24895539, 2014). "As demonstrated in recent years, single nucleotide polymorphisms (SNPs) of the genes encoding adiponectin and tumor necrosis factor-α (TNF-α) may increase the risk of cardiovascular disease in patients with T2DM." (PMID 24669260, 2014). "TNF-α-mediated processes may be more involved in the complications associated with T2D such as cardiovascular disease." (PMID 23984304, 2013). "CRP has emerged as the most promising cardiovascular event risk marker that may amplify the risk of T2DM and death from cardiovascular disorder, while TNF-α has served as a known mediator of IR." (PMID 23825680, 2013).
cardiovascular disease (continued). "Circulating elevated levels of inflammatory markers, such as CRP, TNF-alpha, and IL-6, are associated with increased risk of developing cardiovascular disease; even some acute-phase reactants may also contribute to their pathogenesis." (PMID 23690772, 2013). "Our results suggest that by down-regulating inflammatory mediators such as TNF-α at the tissue level, soy IF may reduce the risk of cardiovascular diseases associated with chronic inflammation." (PMID 17825101, 2007). "Hence, the use of TNF-α inhibitors could also be a possible explanation for the lower risk of cardiovascular disease-specific mortality in patients with IMIDs." (PMID 37409280, 2023). "Interestingly, in PCOS, the CD4+CD28null Tc cells are elevated, a cell phenotype with proinflammatory functions, producing high levels of IFN-γ, TNF-α, and IL-2, all of which are cardiovascular disease risk factors, adding to the association between inflammation and PCOS." (PMID 37195871, 2023). "The expression of pro-inflammatory cytokines, such as TNF-α, IL-1β and IL-6, has been found to be up-regulated in the large elastic arteries of old mice and humans, and may therefore be associated with age-related cardiovascular disease." (PMID 36465181, 2022). "TNF-alpha plays a crucial role in initiating inflammatoryprocesses leading to severe impairment of glucose tolerance and insulinsensitivity which may eventually increase the risk of cardiovascular diseases inT2DM." (PMID 39077619, 2022). "Additionally, when tested in vitro, these metabolites ameliorate TNF-α induced inflammation in human aortic endothelial cells, a mechanism which may reduce the risk of cardiovascular disease." (PMID 24410903, 2014). "This protection provided by soy IF occurred in conjunction with down-regulating TNF-α expression in both bone and vascular tissue suggesting that TNF-α may serve as a key link between the concomitant bone loss and development of cardiovascular disease in conditions of chronic inflammation." (PMID 17825101, 2007). "Tumor necrosis factor-alpha (TNFα) is a pro-inflammatory cytokine predominantly produced by monocytes and macrophages, playing a critical role in the pathophysiology of cardiovascular diseases (CVDs)." (PMID 40244022, 2025). "This article comprehensively examines the role of integrins in the pathogenesis of cardiovascular diseases, focusing on their dysfunction in endothelial cells and interactions with inflammatory mediators, such as TNF-α." (PMID 40001536, 2025). "TNF-a, sometimes referred to as the transducer of cardiovascular disorders, specifically pCAD, controls the expression of adhesion molecules and cytokine networks as well as several signal transduction pathways." (PMID 40218291, 2025). "Advanced age and cardiovascular disease significantly increased IL-6 and TNF-α levels while reducing IgG levels." (PMID 40137715, 2025). "Because of the high burden of vascular inflammation and associated cardiovascular disease (CVD) in RA, effects of CURC vs. TEO on tumor necrosis factor-alpha (TNFα)-driven activation of human vascular endothelial cells were explored." (PMID 40278395, 2025). "By reducing inflammatory cytokines such as IL-6 and TNF-α, SCC addresses a key driver of metabolic and cardiovascular diseases associated with air pollution exposure." (PMID 40005045, 2025). "In fact, recent studies have highlighted the potential of both TNF-α and IL-1β as therapeutic targets for the prevention of cardiovascular diseases." (PMID 39877523, 2025). "Th1 cells, by secreting IFN-γ and TNF-α, stimulate inflammatory responses that increase plaque instability and exacerbate cardiovascular diseases." (PMID 40643541, 2025). "A possible explanation lies in the fact that regular PA stimulates the release of myokines, which regulate inflammatory markers such as TNF-α, IL-6, IL-1β, and CRP, all of which are associated with cardiovascular disease." (PMID 40868631, 2025).
cardiovascular disease (continued). "In cardiovascular disease patients, a recent meta-analysis showed that statins, regardless of dose, resulted in a statistically significant reduction in TNFα concentrations." (PMID 40868832, 2025). "Levels of Tumor Necrosis Factor-alpha (TNF-α) escalate in correlation with the severity of cardiovascular diseases." (PMID 39677041, 2024). "TNF-α interferes with insulin pathways, fostering a state of chronic inflammation that can lead to complications such as cardiovascular disease." (PMID 39840100, 2024). "Studies have previously reported that the incidence of cardiovascular disease was less in patients treated with ABT compared with those treated with TNF inhibitors." (PMID 38627782, 2024). "Epicardial adipose tissue (EAT) releases adipocytokines, such as tumor necrosis factor alpha (TNFα), which play an important role in cardiovascular disease." (PMID 39664126, 2024). "Among the many proinflammatory cytokines, the role of TNF-α has been well studied in the pathophysiology of cardiovascular diseases (CVDs)." (PMID 38791128, 2024). "Although there is ample evidence which demonstrates that inhibiting TNF-α can be effective in treating some cardiovascular diseases, the use of TNF inhibitors in these disease conditions is not yet approved." (PMID 38611112, 2024). "The negative and significant relationship in young women is in line with a previous study, in which patients with cardiovascular diseases with lower cortisol levels upon waking showed higher levels of TNF-α." (PMID 37991642, 2024). "The therapeutic modulation of TNF-α remains a promising but challenging approach, highlighting the need for a deeper understanding of its precise roles in different stages of cardiovascular disease." (PMID 39519510, 2024). "A study using proteomic analysis of biomarkers of cardiovascular disease also confirmed that the IL-1β/TNF-α/IL-6/CRP pro-inflammatory pathway was significantly associated with women suffering from angina pectoris combined with CMVD." (PMID 38836066, 2024). "Patients with cardiovascular disease often have high concentrations of the blood tumor necrosis factor (TNF)." (PMID 37108160, 2023). "Inflammaging, characterized by increased expression of pro-inflammatory cytokines, IL-1, IL-6, and TNF-α, was demonstrated in elderly people with cardiovascular diseases." (PMID 37676301, 2023). "We first assessed CAEC pro-inflammatory cytokine production for IL-6, TNF-α, IL-18 and IL-1β, which are four important players for the development of cardiovascular diseases together with the anti-inflammatory cytokine IL-10." (PMID 36992409, 2023). "TNF, tumor necrosis factor, is a pro-inflammatory cytokine that plays a crucial role in the pathological processes involved in cardiovascular diseases." (PMID 36984421, 2023). "Pro-inflammatory cytokines such as tumor necrosis factor alpha and interleukin-6, involved in the pathogenesis of RA, are also independently predictive of subsequent cardiovascular disease (CVD)." (PMID 36983855, 2023). "TNF-α activation decreases tight junction integrity and leads to leukocytes extravasation and to related cardiovascular diseases." (PMID 36674700, 2023). "So, the roles of TNF-α and IL-6 in VSMCs are complex, and their implications for cardiovascular diseases are significant." (PMID 37873791, 2023). "Adiponectin, a hormone derived from adipocytes, is thought to play a protective role in cardiovascular diseases by decreasing inflammatory cytokines such as tumor necrosis factor α levels and the inhibition of NF-κβ activity." (PMID 37887866, 2023). "Since inflammation plays a crucial role in cardiovascular diseases, we further utilized ELISA to measure the levels of IL-6, IL-1β, and TNF-α in the supernatant of cells after cGAS knockdown." (PMID 38124089, 2023).